LZTS1 (leucine zipper tumor suppressor 1)
Description:
Involved in the regulation of cell growth. May stabilize the active CDC2-cyclin B1 complex and thereby contribute to the regulation of the cell cycle and the prevention of uncontrolled cell proliferation. May act as a tumor suppressor.
Synonyms: FEZ1; F37
Tractability: Antibody: UniProt places it where antibodies can reach, with medium confidence; its Gene Ontology location is reachable by antibodies, with medium confidence; the Human Protein Atlas places it where antibodies can reach. PROTAC: ubiquitination databases record sites on it; its protein half-life has been measured.
Gene: Protein-coding gene on chromosome 8 (20,246,165 to 20,303,963, reverse strand). Ensembl gene ENSG00000061337.
Subcellular location: Cytoplasm; Cell membrane; Cell projection, dendritic spine; Postsynaptic density; Synapse
Subcellular location (Human Protein Atlas): Plasma membrane; Nucleoli
Gene Ontology:
Molecular function: protein binding
Biological process: negative regulation of macroautophagy; regulation of dendrite morphogenesis; regulation of synaptic plasticity; regulation of postsynapse assembly
Cellular component: dendritic spine; cytoplasm; glutamatergic synapse; plasma membrane; postsynaptic density; synapse
Genetic constraint (gnomAD): Loss-of-function variants: 31 observed, 41.57 expected, observed/expected ratio (o/e) 0.75, 90% interval 0.56 to 1.01. The upper end of that interval is the gene's LOEUF score, 1.01, which puts it in group 4 of 6, group 1 being the genes least tolerant of losing a copy. Missense variants: 821 observed, 777.57 expected, observed/expected ratio (o/e) 1.06, 90% interval 1 to 1.12. Synonymous variants: 359 observed, 348.19 expected, observed/expected ratio (o/e) 1.03, 90% interval 0.94 to 1.12.
Homologues: Orthologues: chimpanzee LZTS1 (99% identical), macaque LZTS1 (99% identical), pig LZTS1 (92% identical), dog LZTS1 (92% identical), guinea pig LZTS1 (90% identical), rat Lzts1 (90% identical), mouse Lzts1 (90% identical), rabbit LZTS1 (85% identical), zebrafish lzts1 (46% identical), Drosophila melanogaster CG15365 (22% identical), Caenorhabditis elegans F35B3.7 (15% identical). Paralogues in human: LZTS2 (39% identical), LZTS3 (33% identical).
Diseases named in the same sentence as LZTS1 in open-access papers:
LZTS1 is named in the same sentence as 43 diseases in open-access papers, as found by Europe PMC text mining. Sharing a sentence is not in itself a finding about the gene and the disease. The quoted sentences say what the papers report.
breast carcinoma (12 papers, 2007 to 2025). "To explore the clinico-pathological and therapeutic significance of this association, we investigated Lzts1 expression using the Oncomine database and immunohistochemical analysis in a large series of breast cancers." (PMID 24448468, 2014). "Lzts1 was significantly downregulated in breast cancer (p<0.001), and its deregulation was associated to a higher incidence of tumor recurrence (p=0.039) and of bone marrow metastases (42.1% vs 16.7%)." (PMID 24448468, 2014). "Lzts1 was significantly downregulated in breast cancer samples and its deregulation was associated with a higher incidence of tumor recurrence, and to a worse overall survival." (PMID 24448468, 2014). "In our seminal report, we described a significant loss of Lzts1 expression in breast cancer samples and cell lines." (PMID 24448468, 2014). "In addition, down-regulation of LZTS1 is associated with poor prognosis in human breast carcinoma." (PMID 25938461, 2015). "Previous studies have shown that LZTS1 expression levels are downregulated in breast cancer tissue and cell lines." (PMID 25813822, 2015). "Expression of leucine zipper putative tumor suppressor 1 (LZTS1) was frequently lost or reduced in breast cancer tissues." (PMID 25813822, 2015). "Many studies have shown that LZTS1 expression is downregulated in different types of human cancers, including cancers of the breast, gastric, lung, bladder, oral cavity, prostate, and kidney." (PMID 25813822, 2015). "We further analyzed Lzts1 expression by immunohistochemistry in 270 primary breast cancer samples and 16 normal breast specimens." (PMID 24448468, 2014). "We have further characterized Lzts1 as a putative protein responsible for taxanes resistance in breast cancer cells by affecting microtubule network." (PMID 24448468, 2014). "In previous studies, we have identified LZTS1, as a tumor suppressor gene mapping on chromosome 8p22, whose expression is altered in different human malignancies, including breast cancer." (PMID 24448468, 2014). "As an example, we checked the 5hmC levels of two tumor suppressors: LZTS1 in breast cancer and XPO4 in liver cancer." (PMID 25248841, 2014). "In this study, we investigated Lzts1 role in taxanes-resistance in breast cancer, targeting endogenous LZTS1 by shRNA in MCF7, MDA-MC231, MDA-MB463, and T-47D breast cancer cells." (PMID 24448468, 2014). "To test Lzts1 role in taxanes resistance in breast cancer, we investigate Lzts1 deregulation impact on taxanes sensitivity in four breast cancer cell lines (MCF7, MDA-MB-231, MDA-MB-436, and T-47D)." (PMID 24448468, 2014). "Several recent studies pinpointed a significant downregulation of Lzts1 in human tumors, as well as in breast cancer." (PMID 24448468, 2014). "The quantitative detection of LZTS1 might be useful for predicting potential of breast cancer metastasis." (PMID 25813822, 2015). "We investigate the role of Lzts1 in paclitaxel-resistance in breast cancer cells." (PMID 24448468, 2014). "Lzts1 was significantly downregulated in breast cancer samples (p<0.001)." (PMID 24448468, 2014). "Lzts1 downregulation decreases sensitivity to paclitaxel in breast cancer cell lines." (PMID 24448468, 2014). "In this study, Lzts1 expression was tested in a large series of breast cancer cases." (PMID 24448468, 2014). "Lzts1 immunohistochemical evaluation could be useful as a prognostic tool for clinical applications in breast cancer therapy." (PMID 24448468, 2014). "Previous studies reported that LZTS1 is frequently down-regulated in several solid tumors, and hypermethylation of a CpG island in the LZTS1 promoter is frequently observed in cell lines and tumors which could be responsible for the reduced expression of LZTS1 in breast cancer cells." (PMID 24525428, 2014). "Lzts1 downregulation was established by the use of shRNA (shLzts1) in MCF7, MDA-MB-321, MDA-MD-436, and T-47D human breast cancer cell lines." (PMID 24448468, 2014).
breast carcinoma (continued). "To evaluate the potential use of Lzts1 as a biomarker for the response of breast cancer to paclitaxel treatment, we target endogenous LZTS1 by shRNA in MCF7, MDA-MC231, MDA-MB463, and T-47D breast cancer cells." (PMID 24448468, 2014). "Lzts1 expression is ubiquitously detected in normal tissues, but it is frequently downregulated or absent in different human cancers, including breast cancer." (PMID 24448468, 2014). "Knockdown of endogenous LZTS1 caused resistance to paclitaxel in MCF7, MDA-MB231 and T47D breast cancer cells, but not in MDA-MB436 where Lzts1 expression remained unchanged." (PMID 24448468, 2014).
lung cancer (6 papers, 2014 to 2021). A malignant neoplasm involving the lung. "For instance, microRNA-135b promotes lung cancer metastasis by targeting tumour suppressor LZTS1 and multiple key components in the Hippo pathway such as LATS2, β-TrCP and NDR223." (PMID 26395400, 2015). "LZTS1 is a tumor suppressor gene that is regulated by miR-135b in lung cancer, but the relationship and functional roles of the miR-135b/LZTS1 axis in cSCC were unknown." (PMID 25938461, 2015). "Four of these markers (BRAF, EGFR, LZTS1, and FGF19) have been directly correlated with lung cancer development and progression." (PMID 25397880, 2014).
colorectal cancer (5 papers, 2018 to 2024). A primary or metastatic malignant neoplasm that affects the colon or rectum. "LZTS1 has been previous reported to suppress colorectal cancer proliferation and metastasis." (PMID 37237274, 2023).
prostate carcinoma (4 papers, 2007 to 2021). A carcinoma that arises from epithelial cells of the prostate gland. "To further demonstrate the role of CDC25C, we used pharmacological inhibitors of PLK1 and CHEK1, in our LZTS1-deficient Docetaxel resistant prostate cancer cells." (PMID 24525428, 2014). "Four of these SNP were statistically significant for association with prostate cancer (P < 0.04), supporting a role of LZTS1 in prostate cancer risk." (PMID 17718912, 2007). "More recently a detailed DNA sequence analysis of LZTS1 was performed in a screening panel consisting of sporadic and hereditary prostate cancer (HPC) cases and unaffected controls." (PMID 17718912, 2007).
ovarian carcinoma (3 papers, 2007 to 2024). A malignant neoplasm originating from the surface ovarian epithelium. "Intriguingly, decreased expression of LZTS1 reflects a higher rate of complete response to platinum–taxane‐based chemotherapy than non‐taxane‐based treatment in patients with ovarian cancer, indicating that a decreased LZTS1 level favours chemotherapy response in ovarian cancer." (PMID 39023696, 2024). "It has been reported that the expression of LZTS1 is not decreased in ovarian cancer cells, compared to normal ovarian surface epithelial cells, indicating that LZTS1 is not the target of LOH at 8p22 in ovarian cancer." (PMID 39023696, 2024).
breast tumors (2 papers, 2007 to 2015). "The neoplasms in Lzts1-/- mice were breast tumors, hepatocellular carcinomas, lymphomas, soft tissue sarcomas, and lung adenomas, a spectrum suggesting that Lzts1 absence affects multiple cell types in vivo." (PMID 17718912, 2007). "Hypermethylation of the LZTS1 transcription start site did not exhibit an association with expression in TCGA breast tumours; however, FOXA1 (R2 ≤ 0.75 and 0.67 for regions A and B, respectively) and CIRBP (R2 ≤ 0.212) both exhibited loss of expression with increased methylation." (PMID 25960784, 2015).
glioma (2 papers, 2017 to 2023). A benign or malignant brain and spinal cord tumor that arises from glial cells (astrocytes, oligodendrocytes, ependymal cells). "Notably, gliomas with Class I alterations were enriched for transcripts associated with MEK functional activation (e.g., ETV4, LZTS1), which can also be markers of MEK inhibitor sensitivity." (PMID 36854806, 2023). "Of these 8 genes, 6 (SULT4A1, NDRG4, GAP43, BEX1, HINT1, LZTS1) are believed to act as tumor suppressants, while the remaining two, PKM and VIPR1, have been found to be overexpressed in glioma." (PMID 28957313, 2017).
kidney carcinomas (2 papers, 2004 to 2015). Primary or metastatic malignant neoplasm involving the kidney. "This fits with previous reports of decreased LZTS1 expression in multiple other tumor types e.g., lung, breast, prostate and kidney carcinomas, in which LZTS1 levels were negatively correlated with tumor progression." (PMID 25938461, 2015).
lymph node metastasis (2 papers, 2015 to 2024). "The expression of LZTS1 protein in IMPC tissue was inversely associated with IMPC lymph node metastasis (rs = −0.210, P = 0.036) and lymph node grade (rs = −0.265, P = 0.008)." (PMID 25813822, 2015). "We found that LZTS1 expression was reduced or lost in IMPC, and reduced LZTS1 expression was associated with lymph node metastasis." (PMID 25813822, 2015). "Our own data confirmed that LZTS1 expression was reduced or lost in IDC, and reduced LZTS1 expression was associated with lymph node metastasis." (PMID 25813822, 2015). "Interestingly, the increment of LZTS1 expression is more in endometrial cancer patients without lymph node metastasis, compared to endometrial cancer patients with lymph node metastasis." (PMID 39023696, 2024).
osteosarcoma (2 papers, 2017). A usually aggressive malignant bone-forming mesenchymal neoplasm, predominantly affecting adolescents and young adults. "miR-214 binds directly to the 3′UTR of LZTS1 mRNA to suppress its expression at both the transcriptional and translational levels, thus promoting osteosarcoma cell proliferation, invasion and tumor growth." (PMID 29093516, 2017). "In osteosarcoma, miR-214 promotes cell proliferation and invasion by regulating LZTS1 expression." (PMID 29113367, 2017).
pancreatic cancer (2 papers, 2022 to 2024). "In keeping with this finding, one study reported that overexpression of LZTS1 upregulates the activity of the AKT/GSK‐3β signalling pathway in pancreatic cancer cells." (PMID 39023696, 2024). "On the other hand, emerging evidence suggests that LZTS1 shows higher expression in pancreatic tumour tissue compared to paired normal tissue, indicating the oncogenic function of LZTS1 in human cancers." (PMID 39023696, 2024). "Leucine zipper tumor suppressor 1 (LZTS1) inhibits apoptosis of pancreatic cancer cells by inactivating AKT/GSK-3." (PMID 36139919, 2022). "Furthermore, inhibition of LZTS1 reduced the activity of AKT and its downstream target glycogen synthase kinase 3 β (GSK‐3β) in pancreatic cancer cells, while overexpressed LZTS1 led to upregulated activity of AKT and GSK‐3β." (PMID 39023696, 2024).
bladder cancers (1 paper, 2024). "Since LZTS1 is located at chromosome 8p22, a region of frequent loss of heterozygosity (LOH) in human cancers like breast and bladder cancers, LZTS1 is widely considered a tumour suppressor." (PMID 39023696, 2024).
colon adenocarcinoma (1 paper, 2024). "Next, we evaluated the correlation between LZTS1 expression and clinical features of other CRCs (colon adenocarcinoma: COAD; rectal adenocarcinoma: READ)." (PMID 39023696, 2024).
esophageal cancer (1 paper, 2007). A primary or metastatic malignant neoplasm involving the esophagus. "Investigation of this region, in primary esophageal cancer, has allowed the identification of the human FEZ1/LZTS1 (Leucine-Zipper Tumor Suppressor 1) gene at chromosome 8p22." (PMID 17718912, 2007).
lung adenocarcinoma (1 paper, 2007). A carcinoma that arises from the lung and is characterized by the presence of malignant glandular epithelial cells. "Because DNA methylation of LZTS1 is reduced in tumors it is not a candidate for a positive lung adenocarcinoma marker and it was not studied further at this time." (PMID 17967182, 2007).
metastatic disease (1 paper, 2014). "In recent years, Lzts1 has been shown to be associated to metastatic disease and a worse patients overall survival." (PMID 24448468, 2014).
mucinous adenocarcinoma (1 paper, 2024). An invasive adenocarcinoma composed of malignant glandular cells which contain intracytoplasmic mucin. "Although both adenocarcinoma tissues and mucinous adenocarcinoma tissues showed higher LZTS1 expression than that of the paired normal tissues, the increased degree of LZTS1 expression in adenocarcinoma tissues was much stronger than mucinous adenocarcinoma tissues." (PMID 39023696, 2024).
non-small cell lung carcinoma (1 paper, 2015). A group of at least three distinct histological types of lung cancer, including non-small cell squamous cell carcinoma, adenocarcinoma, and large cell carcinoma. "LZTS1 has recently been identified as a miR-135b target-gene in non-small-cell lung carcinoma that significantly correlates with patient survival." (PMID 25938461, 2015).
oesophageal cancer (1 paper, 2020). "Somatic variants in LZTS1 have been associated primary oesophageal cancer." (PMID 32586322, 2020).
tumor (30 papers, 2002 to 2025). "In CRC tissues, LZTS1 overexpression was significantly correlated to several clinical indices linked to tumour progression like tumour grade and lymph node status." (PMID 39023696, 2024). "Recently LZTS1 has been identified as a target-gene of miR-135b and has been implicated in tumor growth, motility, and invasiveness in multiple tumors." (PMID 25938461, 2015). "Lzts1 deregulation (0/1+ cases) was associated to a higher incidence of tumor recurrence (p=0.039) and to a worse overall survival (p=0.022)." (PMID 24448468, 2014). "Other studies showed that Lzts1 protein was lost or reduced in 68% (70/103 cases) of lung cancer with different histotypes, with a positive association with the tumor grade." (PMID 17718912, 2007). "Thus, these tumor cells retained the mutated LZTS1 allele and lost the normal LZTS1 allele by point mutation." (PMID 17718912, 2007). "Upregulated expression of miR-214 in tumors is linked to tumor progression and poor prognosis in OS and a proposed mechanism of action is that miR-214 promotes OS proliferation and invasion through direct suppression of leucine zipper, putative tumor suppressor 1 (LZTS1) 19,20." (PMID 25784290, 2015). "Importantly, LZTS1 is present on chromosome 8p, and in many cancers, deletion of chromosome 8p12-22 or DNA hypermethylation of this region are associated with a more aggressive tumor phenotype, tumor progression and more rapid appearance of metastases." (PMID 24525428, 2014). "In tumor tissues, researchers found that reduced TET1 expression led to lower levels of 5hmC and mRNA for LZTS1, a well-known tumor suppressor gene associated with breast cancer progression and metastasis." (PMID 40014756, 2025). "Wielscher et al31 found decreased mRNA expression of both leucine zipper tumor suppressor 1 (LZTS1) and TET1 in tumor samples, with reductions in 5hmC levels linked to unfavorable histopathological features, including lymph node involvement." (PMID 40520993, 2025). "HIVEP3, a transcription factor, binds to genes involve in cell progression and differentiation, while LZTS1 acts as a tumor suppressor." (PMID 40463504, 2025). "Across different tumour grades (T1–T3), increased expression of LZTS1 was observed in CRC tissues compared to normal tissues." (PMID 39023696, 2024). "On the other hand, the BRCA and KIRP tumour samples displayed downregulated LZTS1 expression compared to normal tissues." (PMID 39023696, 2024). "In male CRC patients, LZTS1 expression was significantly increased in tumour tissues versus normal tissues, and its expression level also showed an upregulation trend in female CRC patients." (PMID 39023696, 2024). "Accordingly, CRC tumour samples harbour a higher promoter methylation level of LZTS1 than that in the paired normal tissue." (PMID 39023696, 2024). "Since the expression of LZTS1 has been reported as a potential tumour suppressor gene in several cancer types, we first analysed the expression of LZTS1 in pan‐cancer based on the TCGA database." (PMID 39023696, 2024). "In both male and female patients with COAD or READ, LZTS1 expression was upregulated in tumorous tissues compared to normal surrounding tissues." (PMID 39023696, 2024). "In keeping with bioinformatic analysis in tumour samples, LZTS1 promotes the PI3K‐AKT signalling pathway and EMT process, thus contributing to oncogenesis." (PMID 39023696, 2024). "In both COAD and READ, LZTS1 expression revealed a substantial upregulation trend as tumour grade increased, compared to normal tissues." (PMID 39023696, 2024). "Although leucine zipper tumour suppressor 1 (LZTS1) has been considered a potential tumour suppressor, accumulating evidence suggests that LZTS1 is highly expressed in many cancer types." (PMID 39023696, 2024). "Within this region, there are established tumor suppressors (DLC1, DOK2 and LZTS1), as well as potential tumor suppressor genes (CSMD1, MTUS1, and MSR1), and many other genes not established in cancers." (PMID 35994499, 2022).